NOTCH1 (notch receptor 1)
Diseases named in the same sentence as NOTCH1 in open-access papers (continued):
Sharing a sentence is not in itself a finding about the gene and the disease.
cancer (continued). "Among nine cancer-associated mutations that determine sensitivity to ATRA (Notch 1, BCR_ABL, KIT, FLT3, APC, TET2, K-ras, ALK, MLL_AFF1), KRAS, APC, and KIT mutations are associated with resistance to ATRA (only K-ras is shown)." (PMID 23982413, 2013). "In conclusion, NOTCH1, a prominent candidate for radiation-related effects, and other cancer-related proteins were associated weakly to moderately with exposure to radon and arsenic." (PMID 23028920, 2012). "For example, recent studies have found that NOTCH1 mutations, despite conferring fitness advantages that promote clonal expansion, minimally alter cancer risk and thus could be protective." (PMID 40060430, 2025). "The association between NOTCH1 and radiosensitivity has been reported in various types of cancers." (PMID 41306984, 2025). "Markers like Notch1/2/3/4 expression may serve as prognostic indicators in high-risk subgroups of cancer patients." (PMID 40231252, 2025). "Constant Notch1 activation caused the cell-differentiation profiles to change toward multilineage progenitors, suggesting a role for exosomal esNotch1 in maintaining cancer cell fate and differentiation." (PMID 40182121, 2025). "Since previous studies have primarily investigated esophageal tissues with Notch1 mutations, further research in various cancer models is required to elucidate the potential cancer-protective role of mutant clones with cancer driver mutations in normal tissues." (PMID 39200957, 2024). "Both KMT2D and NOTCH1 mutations are present in various cancer types." (PMID 39769182, 2024). "Despite studies describing the association between cadherins and cancer progression, whether cadherins are involved in Notch1 signalling pathways and their pathological implications in GC progression and metastasis remain poorly investigated." (PMID 39172098, 2024). "Notch1 signaling is responsible for regulating cell differentiation, proliferation, and apoptosis, and its abnormal activation has been linked to the development and progression of various cancers." (PMID 38731894, 2024). "Interestingly, recurrent mutations of ARID1A and NOTCH1 have been frequently associated with many types of cancer." (PMID 38043798, 2024). "Besides Notch1, several other signaling pathways and small molecules have dominated the last ten years in research on cancer-carrying PEST domain mutations." (PMID 38255842, 2024). "Therefore, GSIs that target the NOTCH receptors have been implemented in cancers, where NOTCH1 mutations are common (e.g., T-ALL and CLL)." (PMID 38053150, 2023). "Besides cancers, among the dysfunctions linked with abnormal Notch1 signalling are muscle, bone, cerebrovascular, and neurodegenerative diseases." (PMID 37628760, 2023). "Next, we assessed whether cancer cachexia in humans is also linked to increased endothelial Notch1 signaling." (PMID 37749321, 2023). "Additionally, five cancer-associated genes (NOTCH1, MYC, NUMA1, PLAG1, and RAD21) were identified as the most frequently with gain, and SMARCA4 with loss." (PMID 38069131, 2023). "Activating NOTCH1 mutations have been identified in different cancer types." (PMID 36980614, 2023). "Moreover, Jagged1 is also implicated in inducing partial EMT and cancer stem cell traits and propagating these aggressive traits to neighboring cells via Notch1-Jagged1 signaling." (PMID 35480877, 2022). "Thus, cells with NOTCH1 mutations give rise to cancer at a rate that is substantially less than would be expected by chance." (PMID 35726685, 2022).
cancer (continued). "Pacholewska and colleagues investigated DNA methylation profiles in SF3B1-mutated CLL patients, identifying differentially methylated regions associated with multiple cancer-related signaling genes, including NOTCH1, and enriched within the NOTCH signaling pathway." (PMID 35740661, 2022). "However, there are additional disordered drivers that are altered via more complex genetic mechanisms in cancer, such as specific frameshift mutations (e.g., NOTCH1), chromosomal translocations (e.g., BCR, ERG) or copy number variations (e.g., p14ARF)." (PMID 33806614, 2021). "Notch1 is an essential gene for cancer stem cell genesis and is a hallmark of TNBC." (PMID 34922602, 2021). "By contrast, NOTCH1 mutations are several fold more common in normal oesophagus than in cancers, hinting that the loss of NOTCH1 function may impede malignant transformation." (PMID 34637643, 2021). "FOXA1 has also been implicated in the regulation of NOTCH1 in other cancer types." (PMID 34831307, 2021). "Moreover, elevated NOTCH1 levels were significantly associated with chemotherapy-enriched cancer stem cell (CSC) populations, resulting in chemo-resistant HNSCC." (PMID 33322834, 2020). "By providing adaptation to the age‐altered tissue landscape, Notch1 mutations improve the fitness of esophageal epithelial progenitors, filling up the niche with cells that are less likely to be further improved by additional cancer‐promoting mutations." (PMID 30848555, 2019). "We hypothesize that by providing an adaptation to the aged esophageal tissue environment, Notch1 mutations offer a less malignant alternative to a more oncogenic path, thus reducing cancer risk (at least until older ages)." (PMID 30848555, 2019). "Notch1 activating mutations have been reported in various cancers." (PMID 30231940, 2018). "NOTCH1 is one of the highly significant mutated genes in Cancer." (PMID 30181806, 2018). "Additional private clonal mutations were found in each of the components, including a frameshift mutation affecting NOTCH1, which was coupled with loss of heterozygosity of its wild-type allele due to the truncal 9q loss, and a loss of chromosome 10 restricted to the carcinoma." (PMID 29739933, 2018). "JAG1 encodes a ligand for receptor Notch 1, functioning in the Notch signaling pathway which is important for multiple cellular functions, especially during normal development and pathogenesis of cancer." (PMID 28828242, 2017). "Together, our data suggest that PRDM14 expands a progenitor cell population while promoting a permissive epigenetic state for the creation of driver mutations (here, in Notch1), enabling cancer development through the misappropriation of endogenous cellular DNA recombination machinery." (PMID 27106930, 2016). "Moreover, based on accumulating structural information of the NOTCH receptor, the functional consequences of NOTCH1 gene mutations identified from diverse SCCs are analyzed, emphasizing loss of function of Notch in these cancers." (PMID 27228302, 2016). "Moreover, high sensitivity to gamma secretase inhibitor (GSI) PF-03084014 was observed in xenograft model from patient-derived cancer with Notch1 mutation." (PMID 26121683, 2015). "Cancer xenografts and associated gain-of-function mutations in NOTCH1." (PMID 23825651, 2013). "Interestingly, Ddr1 has been implicated in a number of different human cancers, possibly enhancing cell proliferation via direct activation of canonical Notch1 signaling." (PMID 24391948, 2013).
cancer (continued). "Similarly, there is evidence that NOTCH1 mutations drive clonal expansions in skin and squamous esophageal tissue, but may even protect against the evolution of cancer." (PMID 40680084, 2025). "Although RT-qPCR validated the differential expression of NOTCH1 at the transcript level, further studies using IHC or enzyme-linked immunosorbent assay (ELISA) may provide complementary information about the protein's expression in cancer and control tissues." (PMID 40672020, 2025). "Furthermore, gain-of-function mutations in NOTCH1 have been uncovered in many human cancers." (PMID 38043798, 2024). "Perhaps, clones with NOTCH1 mutations confer a more benign alternative to more malignant mutations, and tissue structures that select for such clones as we age may have been favored by natural selection in order to delay cancer development." (PMID 35726685, 2022). "In addition, we found that biosynthesis of prostaglandins (PGs) and thromboxanes (TXs), synthesis of phosphatidylethanolamine (PE), activation of RAC1, diseases associated with O-glycosylation of proteins, and NOTCH1 signaling in cancer were among the significant pathways." (PMID 35629968, 2022). "So how could loss of Notch1 function impede cancer development?" (PMID 30848555, 2019). "Given that NOTCH1 stability and signaling are controlled by its phosphorylation, the study of kinases that could be implicated in this post-translational modification could help to elucidate the mechanisms controlling NOTCH1 dichotomy in cancer development." (PMID 31597699, 2019). "Aberrant methylation of NOTCH1 may thus lead to a greater risk of smoking-induced cancer." (PMID 28500316, 2017). "Interestingly, these opposing effects of inflammation on NOTCH1 signalling might underlie different mechanisms through which inflammation drives cancer development during sporadic CRC and CAC." (PMID 26864323, 2016). "Following optimization and validation of the test using cancer xenografts bearing diverse NOTCH1 aberrations and normal tissues, we screened a large series of human cancers of unknown NOTCH1 mutational status for activated NOTCH1." (PMID 23825651, 2013). "The Drosophila GXYLT (Shams) transferred xylose onto a specific subset of Notch EGF repeats for negative regulation of Notch signaling, while human GXYLT2 activated Notch1 signaling to promote cancer cell proliferation and invasion." (PMID 41492474, 2026). "The USP28‐targeting small molecule CT1113 exhibits anti‐cancer activity by destabilizing oncogenic NOTCH1 and suppressing SREBP1‐mediated lipogenesis in T‐cell acute lymphoblastic leukemia." (PMID 40855785, 2026). "In nasopharyngeal carcinoma CNE2 cells, EGCG upregulates miR-34a, which directly targets Notch1, thereby suppressing cancer cell proliferation, migration, and invasion." (PMID 41602823, 2026). "Overall, EGCG can directly or indirectly inhibit aberrant Notch activation and downregulate core components such as Notch1 and Hes1, ultimately suppressing cancer progression." (PMID 41602823, 2026). "Our study focused on understanding the role of zinc in regulating Notch1 and P21 levels, particularly in the context of cancer biology." (PMID 40970066, 2025).
cancer (continued). "MicroRNAs (miRNAs) are one of the key factors contributing to the dysregulation of gene expression in cancer; therefore, we further explored the miRNAs that regulate NOTCH1 expression." (PMID 41306984, 2025). "By highlighting the interactions between stress responses and key cellular signaling pathways, such as HIF-1α and NOTCH1, this research underscores the significance of stress responses in cancer biology." (PMID 40302812, 2025). "Among the most significantly associated pathways, the top three were the Notch-HLH transcription pathway (p = 3.11 × 10−6), NOTCH1 Intracellular Domain Regulates Transcription (p = 5.00 × 10−5), and Signaling by NOTCH1 in Cancer (p = 9.76 × 10−5)." (PMID 40724850, 2025). "The BA-niche characteristics emphasized the significant role of cancer-associated fibroblasts (CAFs) and enrichment in pathways promoting EMT, vascular development, TGF-β, Wnt/Notch1 signaling, and extracellular matrix (ECM) organization." (PMID 40675986, 2025). "Among the shared features extracted from multi-omics data, EZH2 and NOTCH1 were identified as high-confidence pan-cancer driver genes, supported by large-scale cancer genomics studies, such as TCGA PanCancer Atlas and COSMIC." (PMID 41470046, 2025). "Specifically, Bacteroides fragilis produces toxins that activate pathways such as NF-κB, SMO, Wnt/β-catenin, and Notch1, in addition to inducing reactive oxygen species (ROS) and DNA damage, all of which contribute to cancer progression." (PMID 40236482, 2025). "Notch1 clonal expansion has been described as anti-oncogenic in the context of the oesophagus, where such clones compete with cancer-drivers to prevent their transformation." (PMID 40386410, 2025). "There is a growing body of evidence suggesting a close connection between Notch1 signalling and chemotherapy resistance in various cancer types." (PMID 40100070, 2025). "Treatment with the siRNA at a concentration of 60 pmol/mL significantly reduced the mRNA expression of AKT, ERK, and Notch1 in cancer cells." (PMID 40575155, 2025). "Has-miR-449a, as an upstream molecule of NOTCH1, exerts an enhancing effect on radiosensitivity, which is consistent with the research trends in other cancer types." (PMID 41306984, 2025). "NOTCH1 is upregulated in malignant tumors, has a central function in progression, and has been shown to promote EMT through Notch ligands named Jagged." (PMID 40679044, 2025). "As a result, 285 SLC52A2+NOTCH1+ cells were clustered from CNV+ cancer cells in GSE131907, representing 65.2% of all the SLC52A2+NOTCH1+ cells selected by Seurat’s WhichCells module." (PMID 41453945, 2025). "We found NOTCH1 and FAT1 as the most mutated genes, as Martincorena's results in normal skin and esophagus, suggesting the presence of a precancerous or cancer invasion field." (PMID 40465458, 2025). "Both HIF-1α and NOTCH1 pathways are known to regulate hypoxia responses, angiogenesis, and cancer stem cell renewal, making them key drivers of aggressive cancer phenotypes 42-44." (PMID 40302812, 2025). "Since then, experimental and clinical studies have demonstrated that NOTCH1 is altered in a range of cancer types, including adenocarcinomas originating in the breast, lung, colorectal mucosa, and ovary." (PMID 40789681, 2025). "Notch1 controls genes involved in early differentiation, leading to different phenotypic consequences depending on the cancer's genetic background." (PMID 41026775, 2025).
cancer (continued). "It has been discovered that miR-34a, miR-34b, and miR-34c show low expression levels in cancer cells MiaPaCa2 and BxPC3, which have elevated levels of target genes Bcl-2 and Notch1/2." (PMID 40699746, 2025). "Knocking out the Notch1 gene in mouse skin leads to epidermal hyperplasia and impaired cell differentiation, resulting in cell cancer." (PMID 41050674, 2025). "Integrative multiomic profiling demonstrated that NOTCH1 is a critical downstream target of YTHDF1 that promotes cancer stemness and chemoresistance." (PMID 41423446, 2025). "In contrast to previous studies that independently examined autophagy and Notch1 signaling in BE or other cancers, our findings mechanistically connect these two processes through ULK1, a key autophagy initiator." (PMID 40629071, 2025). "CD10 and Notch1 are among cancer stem cell regulators, and they have roles in cancer progression and chemoresistance." (PMID 40060224, 2025). "Recent studies have primarily focused on investigating the effects of Notch1 and its ligands on cancer metastasis and drug resistance." (PMID 41315239, 2025). "The enhanced expression of Notch1, Notch2, and Nanog in salispheres and ALDHhighCD44high cells suggests the function of cancer stem cells in ACC." (PMID 40371051, 2025). "Treatment with siRNA at a concentration of 60 pmol/mL significantly decreased the mRNA expression of AKT, ERK, and Notch1 in cancer cells." (PMID 40575155, 2025). "TAM produce IL‐10 which improves the viability of cancer cells in NSCLC by stimulating the JAK1/STAT1/NF‐κB/Notch1 signaling pathway and promoting the expression of SOX‐2 and other genes linked to cancer cells." (PMID 39927632, 2025). "NOTCH1 expression was positively associated with an advanced T stage, neck lymph node metastasis, advanced TNM stage, second primary cancer, and was significantly associated with shorter disease-specific survival (DSS)." (PMID 41009728, 2025). "The drug sensitivities of MT2A, SLC7A5, and NOTCH1 were predicted in this study using the pan-cancer database of oncoPredict." (PMID 40133832, 2025). "Dll4 was expressed in cancer cells and engaged Notch1 signalling in an autocrine way, whereas Jag1 was expressed in neighbouring hepatic stellate cells and engaged Notch2 signalling in neighbouring cancer cells." (PMID 40052152, 2025). "Notch‐1 signalling was also found to regulate cell–cell junctions, which indicates the essential role of Notch‐1 in collective cancer cell migration." (PMID 39343985, 2025). "Notable downregulated genes included Mki67, Ccn1, Muc1, Atf3, Ntrk2, Arid5b, Igf1r, Igf2bp2, Cd47, and Cd37 (oncogenic function) and integrin-related genes, Itga7, Itga11, Itgam and Notch1 (cancer stem cell markers)." (PMID 39946195, 2025). "Significantly downregulated genes included those involved in signaling by NOTCH1 HD domain mutants in cancer, constitutive NOTCH1 HD domain mutants, and signaling by TGF‐beta family members." (PMID 41263494, 2025). "The frequently altered expression of NOTCH1 has been reported as oncogenic in cancers such as lung, T-ALL, colon, breast, ovarian, and hepatocellular cancer and gliomas and is often correlated with poor survival of patients." (PMID 41451346, 2025). "Genes related to cancer proliferation including NOTCH1 (p < 0.05), EP300 (n.s.), and PTCH1 (p < 0.05) were all upregulated in DR‐LSCC." (PMID 40385549, 2025). "As an example, sorted cancer stem cell (CSC) subpopulations of ACC organoids express higher levels of NOTCH1 and NICD1, compared to the unsorted sample." (PMID 40789681, 2025). "Other “Tier 1” cancer-related gene mutations in the COSMIC Cancer Gene Census21 present in the 15 most frequently mutated genes include PIK3R1 (4%), NF1 (4%), NOTCH1 (4%), APC (3%), and ATR (3%)." (PMID 40057511, 2025). "The in vitro data strongly support the blockade of both Notch1 and ChK1 as anti-cancer approach, particularly in MBM where the standard of care is radiation therapy which acts by causing DNA damage and cell death." (PMID 40437523, 2025).